INS (insulin)
Diseases named in the same sentence as INS in open-access papers (continued):
Sharing a sentence is not in itself a finding about the gene and the disease.
Obesity (continued). "Clinical trials are rare to study the efficacy of insulin sensitizer in changing the risk of developing obesity-associated NAFLD, our study thus offered unique preclinical data for answering this important question." (PMID 31749893, 2019). "A higher sodium intake is conceivably associated with insulin resistant conditions like obesity, but associations of non-alcoholic fatty liver disease (NAFLD) with a higher sodium intake determined by 24 hours (24 h) urine collections are still unclear." (PMID 31817623, 2019). "In this regard, selective deficiency of PTP1B in the liver significantly improves insulin sensitivity, thus leading to complete protection against obesity-induced endothelial dysfunction." (PMID 30679477, 2019). "Accordingly, hypothalamic insulin and leptin resistance is a hallmark of obesity and leads to hyperphagia and reduced locomotion." (PMID 29371411, 2018). "Mice with a skeletal muscle CEPT1 deficiency have increased insulin sensitivity and altered muscle tissue lipid compartmentalization with diet-induced obesity." (PMID 29478028, 2018). "Overall, it is well known that insulin is essential for the cognitive development of the brain and its deficiency or resistance in obesity can cause decrease insulin transfer from the peripheral nervous system to the brain hence leading to dementia." (PMID 30042911, 2018). "Chronic Western diet consumption elevated plasma glucose and insulin and caused obesity, diastolic dysfunction, and β-cell dysfunction." (PMID 30116740, 2018). "Not eating breakfast regularly has been associated with increased waist circumference, high fasting insulin, high glucose and obesity in both children and adolescents." (PMID 29444663, 2018). "In this study, LC/MS-based lipid profiling was performed to identify adipose signature of obesity-associated insulin sensitivity, insulin resistant and T2DM." (PMID 29940972, 2018). "In conclusion, this study suggests that, among children with a parental history of obesity, lower SFAs and higher vegetable and fruit intakes are associated with better insulin sensitivity as these children enter puberty." (PMID 30383280, 2018). "Obesity and high insulin levels are associated with lower levels of sex hormone binding globulin (SHBG)." (PMID 29713614, 2018). "Individuals whose cord blood or amniotic fluid insulin levels are elevated have a 3–4 fold risk for developing glucose intolerance, obesity, and type 2 diabetes in late childhood and as adults." (PMID 30201937, 2018). "Chga KO mice has higher level of leptin due to prolonged effect of insulin on Srebp-1c gene expression, causes obesity which was reversed by PST13." (PMID 29880906, 2018). "The present study has addressed this question by investigating possible associations between markers of insulin metabolism and cIMT among children and adolescents with either overweight or obesity." (PMID 30470212, 2018). "Predisposing factors such as insulin antagonism, insulin resistance, glucose tolerance alteration, obesity, hyperadrenocorticism, and persistent use of glucocorticoids are also associated with APN." (PMID 29805204, 2018). "Dysfunction of Tub (tubby bipartite transcription factor) causes late-onset obesity in mice, perhaps due to Tub’s role in insulin signaling." (PMID 30514929, 2018). "Of note, development of severe obesity, liver fat accumulation, and insulin resistance in FFAR4-deficient mice under high-fat diet were accompanied by lower SCD1 gene expression." (PMID 30190473, 2018). "A key player in glucose metabolism and tightly linked to obesity, insulin action has also been investigated in the context of OSA." (PMID 30127766, 2018). "Whole-grain foods, which contain the endosperm, germ, and bran of seeds, have been reported to improve insulin sensitivity and reduce obesity, while they have also been found to be associated with metabolic syndrome in adults." (PMID 29698465, 2018).
Obesity (continued). "Some studies have reported that obesity is positively associated with high bone mass probably as a result of the increased levels of hormones such as leptin, insulin, and estrogen that are known to induce bone growth and inhibit the bone remodeling process." (PMID 30327744, 2018). "Obstructive sleep apnea (OSA) is closely associated with obesity, insulin resistance, and inflammation." (PMID 30151379, 2018). "As obesity and insulin metabolism are closely linked to T2DM, more and more studies have been performed in attempt to investigate the relationship between the Leu72Met polymorphism and T2DM risk across various counties." (PMID 30487812, 2018). "This association was first understood when murine obesity was linked with increased production of the inflammatory, insulin desensitising cytokine: tumour necrosis factor-α (TNF-α)." (PMID 29479350, 2018). "Maternal glucose-insulin metabolism can lead to an increased risk of childhood obesity, and this thus becomes a vicious cycle of obesity from one generation to the next." (PMID 29393863, 2018). "Surprisingly, hepatic NEMO-deficient mice are protected against diet-induced obesity and exhibit improved insulin sensitivity." (PMID 30591653, 2018). "Loss of PTEN leads to constitutive insulin sensitivity and obesity, in addition to high susceptibility to cancer." (PMID 29695257, 2018). "Genome-wide association studies have identified so far more than 40 diabetes-associated loci, which are related to β-cell function, insulin sensitivity, and obesity and respond to approximately 10% of T2D heritability." (PMID 30116154, 2018). "In some of the dog breeds such as Golden Retriever, Dachshund, and Shetland Sheepdog, obesity and DM have an imperative association; as in fully obese dogs, there will be unusual glucose xenophobia and high level of insulin." (PMID 29805204, 2018). "Similar to high-fat diet (HFD) feeding in mammals, a chronic high-sugar diet causes an obesity-like phenotype of increased fat accumulation, impaired fat body insulin signaling, and hyperglycemia in Drosophila larvae." (PMID 29661693, 2018). "Although activation of AMPK in peripheral tissues is able to promote fatty acid oxidation and insulin sensitivity, its chronic activation in the hypothalamus causes obesity by inducing hyperphagia in both humans and rodents." (PMID 30423881, 2018). "In HFD groups, mice fed HFB showed significant phenotype changes associated with diet induced obesity, including impaired glucose and insulin metabolism, enhanced cumulative energy intake, increased level of LDL-C, TC, and TG concentration in serum." (PMID 30319558, 2018). "While hepatic SOCS3 deficiency initially prevents impaired insulin action in diet-induced obesity, these mice have accelerated inflammation at later stages." (PMID 30591653, 2018). "These fatty acids attenuate risk factors related to obesity and particularly contribute to the improvement in insulin sensitivity, blood pressure, endothelial dysfunction, and subclinical inflammatory parameters." (PMID 30037112, 2018). "Human obesity is associated with a reduction in insulin sensitivity, and in turn, a reduced insulin sensitivity has been associated with decreased microbial richness." (PMID 30581426, 2018). "Genetic variability associated with increased obesity, fasting insulin, glycated haemoglobin, triglycerides and propensity to become a smoker were also positively genetically correlated with T2D, CAD and ischaemic stroke." (PMID 29938349, 2018). "For each of the obesity-related traits under investigation, an approximately null estimate for effect was obtained, with the strongest association being shown by fasting insulin." (PMID 29531326, 2018). "In numerous studies from around the world, obesity is associated with metabolic risk factors such as, for example, 2-h glucose and insulin, blood pressure, triglyceride, and HDL cholesterol." (PMID 29692943, 2018).
Obesity (continued). "Serum 25(OH)D concentrations and adipokines were analyzed by ELISA and cardiometabolic risk factors were indexed by obesity, glycemic control, insulin sensitivity, lipid profile, and blood pressure." (PMID 32153911, 2018). "Equine metabolic syndrome (EMS), like human metabolic syndrome, comprises a collection of clinical signs related to obesity, insulin dysregulation and susceptibility to secondary inflammatory disease." (PMID 30001422, 2018). "In other words, mitoQ treatment resulted in a more favorable energetic state requiring less insulin and at least mitigating the demand for obesity associated islet hypertrophy." (PMID 29864244, 2018). "Previous studies investigating growth and metabolism in children born post-term showed a 34% reduction in insulin sensitivity in pre-pubertal children and an increased risk of obesity in adolescence males." (PMID 30154437, 2018). "Otherwise, mice with IL-6Rα deficiency in T cells exhibit improved insulin sensitivity at the onset of diet-induced obesity." (PMID 30591653, 2018). "Current evidence suggests that as little as 10 min of high intensity exercise can improve metabolic health and aerobic capacity and alternative day fasting can reduce obesity-associated changes in body composition, fasting insulin and glucose concentrations." (PMID 29534545, 2018). "Decreased insulin sensitivity and higher obesity risk in young female adults were also reported for early menarche, as well as higher risk for NAFLD, ectopic lipid accumulation, and GDM." (PMID 29780358, 2018). "Other studies have demonstrated increased mTOR/S6K1 activation in the transgenic Zucker obese (ZO) rat, a model of overnutrition and obesity which carries a mutation of the leptin receptor and develops INS resistance and glucose intolerance." (PMID 30116740, 2018). "In obesity, elevated insulin causes fatty liver by activating the gene encoding SREBP-1c, a transcription factor that enhances fatty acid synthesis." (PMID 29952285, 2018). "Nevertheless, our findings showed that CGA treatment activated PPARγ to a degree similar to RG treatment, potentially explaining the ability of CGA to increase insulin sensitivity and inhibit chronic inflammation caused by obesity." (PMID 30627576, 2018). "Previous studies showed that the Leu72Met polymorphism was related to obesity, insulin metabolism, and metabolic syndrome." (PMID 30487812, 2018). "LPA was shown to impair glucose homeostasis and inhibit insulin secretion and is associated to inflammation processes and obesity." (PMID 29856767, 2018). "In order to assess the influence of obesity on regeneration-relevant pathways, the expression levels of genes associated with apoptosis, notch-, insulin-, and sonic hedgehog-signaling were evaluated." (PMID 29441023, 2018). "Several studies have shown that FGF21 overexpression in rodents is associated with weight loss and lower obesity, as well as insulin sensitivity in its target tissues." (PMID 30242179, 2018). "Oversupply of fatty acids to insulin target cells occurs because of excessive dietary intake, obesity, or muscle inactivity-associated decrease in beta oxidation of fatty acids." (PMID 30116482, 2018). "Insulin plays a central role in the regulation of blood glucose and energy homeostasis; however, high levels are associated with hypertension, obesity, dyslipidemia, and glucose intolerance in humans." (PMID 30278087, 2018). "In a recent study using mice expressing only Ins2 (both alleles), mice exhibited compensatory high insulin production from Ins2 genes and developed obesity on a high fat diet." (PMID 30541568, 2018). "The third network contained eight genes from loci identified in T2DM and insulin sensitivity GWAS, with a further three linked with obesity and fasting glucose GWAS loci." (PMID 29986096, 2018). "The insulin/IGF-1 axis plays an important role in the association between obesity and risk of breast cancer." (PMID 29558911, 2018).
Obesity (continued). "Overall, our findings suggest that loss of ANGPTL4 promotes (visceral) obesity yet, by raising insulin levels, reduces glucose intolerance, and that this effect is partly dependent on the gut bacteria." (PMID 29502266, 2018). "Genetic inactivation of insulin gene alleles in mice also lowers their systemic insulin levels and prevents or ameliorates high-fat diet-induced obesity." (PMID 30541568, 2018). "This is also in accordance with the fact that SCD1-deficient or knockout mice are protected from obesity and show increased insulin sensitivity." (PMID 30248999, 2018). "The ability of a single gene controlling FA metabolism in leukocytes to cause measureable changes in obesity and insulin sensitivity at the whole animal level underlines the potential power of altering immunometabolism." (PMID 28661198, 2018). "The strong decrease of chemerin after surgery was associated with an improvement in insulin sensitivity and blood glucose, which further support the key role of this adipokine in mediating metabolic alterations in obesity." (PMID 29618983, 2018). "In turn, M1 cells express Itgax and high levels of iNOS, TNF-α, and IL-6, which impede insulin signaling in adipocytes and promote obesity-associated inflammation and insulin resistance." (PMID 29415997, 2018). "Obesity leads to higher levels of circulating insulin and IGF-1 in the body, which have been associated with risk for ER+ tumors and increased mammographic density in women with BMIs < 25 kg/m2, but not in overweight and obese women." (PMID 29804217, 2018). "We aimed to assess the effect of weight loss during low-calorie diet on insulin sensitivity, AT expression of genes associated with inflammation in young subjects with obesity." (PMID 29737494, 2018). "• In mice, genetic lowering of insulin levels or selective genetic disruption of the insulin receptor in adipocytes causes prevention or remission of obesity." (PMID 30541568, 2018). "Weight loss improves insulin sensitivity by decreasing free fatty acid mobilization and by changing adipokine profile in obesity." (PMID 29473001, 2018). "This is important as there has been recent information suggesting postprandial insulin concentrations are linked to obesity (Carbohydrate-Insulin Model of Obesity)." (PMID 30367639, 2018). "Thirdly, PCA analysis demonstrated that the rates of GU in skeletal muscle, adipose tissue and liver had high loadings on PC1, and that obesity was negatively associated with the rates of GU similarly in all insulin-sensitive tissues in both men and women." (PMID 29535167, 2018). "EIF2S3 has been linked to X linked mental retardation, hypogonadism, obesity, microcephaly and epilepsy and among its related pathways are regulation of lipid metabolism and insulin." (PMID 30213969, 2018). "For example, overweight and obesity are intrinsically linked with prolonged, excessive calorie intake, which overwhelms β-cell insulin production and insulin signaling pathways." (PMID 30373146, 2018). "That obesity and hepatic steatohepatitis are associated with impaired insulin clearance is demonstrated by the repression of hepatic CEACAM1 expression by high-fat (HF) intake via a peroxisome-proliferator-activated receptor α (PPARα)-dependent mechanism." (PMID 30314283, 2018). "Fourthly, increased insulin levels are associated with obesity, and several adipokines have in turn been implicated in the disease pathogenesis of endometrial cancer." (PMID 29533014, 2018). "Since lipolysis inhibition is equivalent to lipogenesis promotion, the effect of insulin on adipocytes is probably responsible for the observed association between hyperinsulinaemia and incident obesity." (PMID 30541568, 2018). "Consistently, when fed a HFD, compared to wild type mice, fat-specific NCoR-deficient mice are prone to obesity yet have enhanced insulin sensitivity." (PMID 30186237, 2018).
Obesity (continued). "The findings here thus pinpoint a novel function of PRKD2 in regulating β-cell insulin secretion in that PRKD2 deficiency primarily increases insulin secretion, and further induces obesity and IR." (PMID 29789568, 2018). "Obesity-associated chronic inflammation is known to be responsible for the impaired insulin sensitivity." (PMID 30596786, 2018). "Given the importance of the fat-liver axis in the pathogenesis of obesity-associated dysmetabolism, we next assessed if the rapid near-normalization of glucose handling, insulin resistance and liver changes were also apparent at the adipose tissue level." (PMID 28360082, 2017). "In the setting of high fat diet-induced obesity, however, β-cell specific loss of the leptin receptor worsened glucose tolerance, impairing both insulin secretion and expansion of β-cell mass." (PMID 28168202, 2017). "Obesity is strongly associated with development of impaired glucose and insulin metabolism, which are also characteristic of AD patients and have been proposed as possible mechanisms driving AD pathogenesis." (PMID 28612048, 2017). "The initial moment of obesity caused important metabolic abnormalities, such aselevated leptin (62.5%) and insulin (40%) levels in the HF group." (PMID 29069204, 2017). "Obesity is frequently associated with the resistance of peripheral tissues (muscle and adipose) to the action of insulin." (PMID 29228058, 2017). "The pathophysiology of T2DM has not been completely understood, and there are views, that link T2DM with insulin signaling deficiencies, obesity and reactive oxygen species (ROS)." (PMID 28693595, 2017). "Circadian wheel running rhythms, body weight, caloric intake, insulin action, and susceptibility to diet-induced obesity were assessed." (PMID 28475596, 2017). "Adiponectin concentrations are low in obesity and are associated with insulin-resistant states in humans and mice." (PMID 29053583, 2017). "Several studies have also associated the RETN rs1862513 polymorphism with obesity, insulin sensitivity, type 2 diabetes, and cerebrovascular disease." (PMID 29386698, 2017). "Obesity and acromegaly are deleterious conditions, associated with high insulin and IGF1 levels, and decreased life expectancy." (PMID 28316059, 2017). "Because T2DM is often associated with obesity and elevated cholesterol contributes to β‐cell dysfunction, this study focused on the effect of increased cholesterol on insulin granule exocytosis." (PMID 28544529, 2017). "Potential mechanisms underlying effects of obesity on breast cancer survival are mediators such as members of the insulin/insulin-like growth factor family, adipocytokines secreted from adipose tissue and inflammatory cytokines." (PMID 29232439, 2017). "Reduction of FABP4 levels has been associated with a better response to insulin and protective effect against obesity." (PMID 28382233, 2017). "On the other hand, Obesity-related accumulation of ectopic fat in key insulin-sensitive organs (e.g., skeletal muscle and viscera) causes changes in the insulin-signaling pathways." (PMID 28542472, 2017). "Twelve weeks postpartum, in these subjects with NEUROD1 variants and obesity, we performed an oral glucose tolerance test; both showed a significant reduction in insulin release at 1 and 2 hours when compared with T2D and control subjects." (PMID 28095440, 2017). "Future studies should focus on region-specific mechanisms of selective hormone resistance, and, ultimately, to develop cell-specific insulin (de)sensitizers in the treatment of obesity-associated alterations such as uncontrolled HGP." (PMID 28469281, 2017). "Common treatments for obesity involving strategies to increase insulin sensitivity have often been associated with improvement of endothelial function and/or endothelial insulin sensitivity." (PMID 28848738, 2017).